FOXD3-AS1 (FOXD3 antisense RNA 1)
Synonyms: pasFOXD3; FAST
Gene: Long non-coding RNA gene on chromosome 1 (63,320,056 to 63,324,801, reverse strand). Ensembl gene ENSG00000230798.
Diseases named in the same sentence as FOXD3-AS1 in open-access papers:
FOXD3-AS1 is named in the same sentence as 3 diseases in open-access papers, as found by Europe PMC text mining. Sharing a sentence is not in itself a finding about the gene and the disease. The quoted sentences say what the papers report.
glioma (1 paper, 2021). A benign or malignant brain and spinal cord tumor that arises from glial cells (astrocytes, oligodendrocytes, ependymal cells). "FOXD3-AS1 is an oncogene that has recently been identified to be involved in several human malignancies, including cutaneous malignant melanoma and glioma." (PMID 34424807, 2021).
cancer (1 paper, 2021). A tumor composed of atypical neoplastic, often pleomorphic cells that invade other tissues. "Long non-coding RNA (lncRNA) FOXD3 antisense RNA 1 (FOXD3-AS1) has been reported to participate in multiple processes that contribute toward the development of cancer." (PMID 34424807, 2021). "LncRNA FOXD3 antisense RNA 1 (FOXD3-AS1) has been recently validated as a tumor promoter in several human cancer types, including colon adenocarcinoma and thyroid cancer." (PMID 34424807, 2021).
FOXD3-AS1 also shares sentences with these, for which no sentence is quoted: lung carcinoma (1 paper).